CDH1 (cadherin 1)
Diseases named in the same sentence as CDH1 in open-access papers (continued):
Sharing a sentence is not in itself a finding about the gene and the disease.
colorectal cancer (continued). "Genome-wide association studies (GWAS) have identified multiple common CRC-related (colorectal cancer) SNPs (single nucleotide polymorphisms) including the Cadherin 1(CDH1) rs9929218 may act by increasing the risk of colorectal cancer, colorectal adenoma, or both." (PMID 33627078, 2021). "Similarly, most CDH1 variants identified here in glioma patients or glioma tissues were previously detected in the germline of patients with cancer of the gastrointestinal tract, such as gastric or colorectal cancer (references listed in Suppl." (PMID 33929593, 2021). "Previous research demonstrated the upregulation of CDH1 in human colorectal cancer cells and the T24 human lineage, and, to the authors knowledge, this is the first time it is described in canine UC cell lines." (PMID 40509054, 2025). "Among these, ZEB1, SPARC, CDH1 and EpCAM were the most significantly differentially expressed genes between TRPS1-WT and TRPS1-MT cells and had been previously associated with colorectal cancer metastasis." (PMID 39307879, 2024). "It has been reported that MYSM1 suppresses colorectal cancer progression via histone H2A deubiquitination, thereby activating miR-200 family members/CDH1." (PMID 38177530, 2024). "MYSM1 as a histone H2A deubiquitinase has been reported to activate the transcription of its downstream genes, including CDH1, c-MET, or genes encoding ribosomal proteins via histone H2A deubiquitination in colorectal cancer, melanoma, and B cell lymphoma." (PMID 38177530, 2024). "Next, we performed immunohistochemical (IHC) staining on genome-sequenced primary human colorectal cancers tissues to evaluate the correlation between the expression of ZEB1, CDH1 and TRPS1 mutation." (PMID 39307879, 2024). "We also report a new signet ring cell colorectal cancer case in a CDH1 carrier and discuss CDH1-related cancer." (PMID 37761816, 2023). "The disease gene association from the CA2 string network for colorectal cancer was found to be prominent with the CTNNB1 (Z-score—7.8) and CDH1 (Z-score—7.2) genes." (PMID 37895185, 2023). "One of such genes is CDH1 (E-cad protein) whose high expression was a predictor of better prognosis for colorectal cancer in agreement with TCGA data." (PMID 37006265, 2023). "A significant correlation between the rs9929218 variant of cadherin-1 (CDH1), TRPML2 and colorectal cancer (CRC) susceptibility has been demonstrated." (PMID 36499683, 2022). "According to previous reports, FOXD4 induces the progression of colorectal cancer by regulating the SNAI3/CDH1 axis and can be used as a marker of colorectal cancer." (PMID 32509568, 2020). "Among them, the regulation of the EMT-associated genes CDH1 and SNAIL were further validated in colorectal cancer cell lines DLD-1 and HT29." (PMID 29880876, 2018). "The down-regulation of E-cadherin (CDH1) is considered as a critical event for the invasion and metastasis of colorectal carcinoma, and the loss of E-cadherin-mediated cell adhesion is one rate-limiting step in the progression from adenoma to carcinoma." (PMID 24979261, 2014). "In colorectal carcinoma, concentrations of Cdh1 and p27 are very low when compared to healthy surrounding tissue, while the expression of Skp2 is inversely higher." (PMID 25000203, 2014). "CDH1 mRNA expression was detected in 39 of 41 (95%) colorectal adenoma samples, in all 10 (100%) colorectal cancer samples and in all 10 (100%) normal colonic mucosa samples." (PMID 23029563, 2012). "As expected, expression of CDH1 mRNA was clearly decreased in colorectal cancer compared to the expression in normal colonic mucosa." (PMID 23029563, 2012). "While trying to link CLP36 and EMT, it has been demonstrated that CLP36 could prevent metastatic potential or EMT of colorectal cancer cells, as seen by the elevated CDH1 expression and the diminished VIM, Snail and ZEB levels." (PMID 39735560, 2024).
colorectal cancer (continued). "In this clinical review, we described the penetrance risks of gastric, breast, prostate, and colorectal cancers, in CDH1 carriers, within as well as outside the familial setting, and the best approaches to manage each risk, using either prophylactic surgery or surveillance." (PMID 35277969, 2022). "There is currently no consensus regarding the overall utility of increased colorectal cancer screening on the basis of CDH1 mutation status alone." (PMID 34073553, 2021). "Moreover, one of the top downregulated genes was mutated in colorectal cancer (MCC), which enhances cell-cell adhesion through interacting with CDH1." (PMID 32824198, 2020). "· CDH1 and Colorectal Carcinoma showed 149 peer-reviewed PubMed articles." (PMID 33062523, 2020). "Moreover, the depletion of RBM47 led to the downregulation of epithelial-associated genes including OCLN, CDH1, TJP1, and CLDN1 with a concomitant enhancement in cell migration, mesenchymal markers, invasion and metastasis in colorectal cancer, which was consistent with our report." (PMID 35831298, 2022). "Although related expression levels in tissue did not correlate with its expression in blood, consistent with previous studies FHIT and TTPAL genes upregulation and CDH1 downregulation, in especially tumoral tissues, may serve as predictive determinants for the patients with colorectal cancer." (PMID 36161592, 2022). "However, the results were inconsistent with results on colorectal cancer (CRC), which showed that CDH1 -160C/A polymorphisms could reduce CRC risk." (PMID 27349965, 2016). "Furthermore, aberrant methylation patterns of the CDH1 promoter region were also described in pre-adenoma stages of colorectal cancer, in hyperplasic polyps and in ulcerative colitis (a chronic inflammatory condition of the large intestine that predisposes to cancer)." (PMID 18702824, 2008). "In colorectal cancer, a lower MYSM1 expression correlates with a better prognosis, as it epigenetically upregulates the miR-200 family and CDH1, subsequently suppressing the PI3K/AKT pathway." (PMID 39684760, 2024). "The presented study analysed the expression of CDH1, PTEN, FHIT, and TTPAL genes using tissue samples and blood of patients with different stages of colorectal cancer (CRC)." (PMID 36161592, 2022). "The main aim of the study is to assess expression levels of CDH1, FHIT, PTEN, and TTPAL genes in tumors and peripheral bloods of colorectal cancer patients in staged I–IV." (PMID 36161592, 2022). "In the current study, we employed two human colorectal cancer cell lines, HT29 and SW480; these cells carry wild-type CDH1 (E-cadherin) and CTNNB1 (β-catenin), but mutant APC, and exhibit active Wnt/β-catenin signaling." (PMID 36072467, 2022). "In patients with high MALAT1 expression, it was found that MALAT1 binds EZH2 to the CDH1 promoter and inhibits miR-218 during oxaliplatin treatment, indirectly promoting EMT, metastasis, and chemoresistance of colorectal cancer cells." (PMID 34199840, 2021). "For that reason, LBC, oral facial clefts, colorectal carcinomas (CRC), and other cancers, have been suggested as suitable for CDH1 screening and early detection of HDGC." (PMID 34066044, 2021). "In colorectal carcinoma, AT1R was correlated with promotion of EMT, because inhibition of AT1R resulted in increase of CDH1 and decrease of ZEB1 and vimentin (mesenchymal markers), while blockage of AT2R caused decrease of CDH1." (PMID 33673178, 2021). "Here, we analyzed the methylation pattern from five colorectal cancer patients from the Amazon state in Brazil for four tumor suppressor genes, viz.: DAPK, CDH1, CDKN2A, and TIMP2 by employing a polymerase chain reaction (PCR) specific to methylation." (PMID 26363785, 2015). "In the present study, we evaluated the methylation of the CDH1, DAPK, CDKN2A, and TIMP2 genes in five colorectal cancer patients from Manaus, the capital of the Amazon state in Brazil." (PMID 26363785, 2015).
colorectal cancer (continued). "In our study EMT was detected in samples of colorectal cancer based on coordinated changes in the expression of the following genes: ZEB1, ZEB2, SNAI1, CDH1, and VIM." (PMID 25157365, 2014). "Our data show that SNAI1 and Twist1 are already expressed in benign precursor lesions of colorectal cancer and that SNAI1 expression was significantly correlated with lower expression of CDH1." (PMID 23029563, 2012). "Down-regulation of E-cadherin (CDH1) and epithelial-mesenchymal transition (EMT) are considered critical events for invasion and metastasis of colorectal carcinoma." (PMID 23029563, 2012). "Of the 10 colorectal carcinomas, two expressed CDH2 mRNA and both showed reduced, but detectable, levels of CDH1 mRNA." (PMID 23029563, 2012). "Mechanistic studies indicate that MYSM1 may epigenetically enhance the expression of the miR-200 family and CDH1, thus inhibiting the PI3K/AKT signaling pathway and reducing the progression of colorectal cancer." (PMID 39684760, 2024). "Nuclear PKM2 binds to TGFB induced factor homeobox 2 (TGIF2), which is a transcription factor of Cadherin-1 (CDH1), and represses CDH1 transcription and stimulates the mesenchymal marker, vimentin, during EMT both in in vitro and in vivo colorectal cancer models." (PMID 31027222, 2019). "We performed a quantitative RT-PCR assay to analyze the mRNA expression of SNAI1 (Snail1), TWIST1 (Twist1), CDH1 (E-cadherin) and CDH2 (N-cadherin) in FFPE tissue samples of colorectal adenomas (n = 41), colorectal cancer (n = 10) and normal colon mucosa (n = 10)." (PMID 23029563, 2012). "Another CDH1 promoter variant, -347insA, has not been associated with sporadic DGC so far, but appears to increase susceptibility to colorectal cancer and to contribute to oesophageal/cardiac cancer risk." (PMID 18482459, 2008). "In our global expression and DNA-binding analysis in the colorectal cancer cell line DLD-1, we found that AP4 binds to the promoters of and up-regulates many EMT effectors and marker genes, such as SNAIL, Vimentin, FOS, LEF1, and N-cadherin, and directly represses CDH1/E-cadherin." (PMID 33567514, 2021). "Interestingly, in colorectal cancer, a strong positive correlation was observed between the expression of THBS2 and genes encoding the EMT markers N-cadherin, vimentin, TWIST1, and SNAIL, while there was a negative correlation with CDH1." (PMID 39857742, 2025).
colon carcinoma (430 papers, 1995 to 2026). "Deletion or silencing of CDH1 (which encodes E-cadherin) is prevalent in prostate, bladder, kidney, breast, stomach, and colon cancers." (PMID 40378957, 2025). "In one study, colon cancer was reported in 3 of 238 (1%) CDH1 pathogenic variant carriers, with 1 case of SRCC." (PMID 34949788, 2022). "CDH1 low expression in colon cancer was associated with short overall survival, although the association was not significant." (PMID 36420658, 2022). "The expression of KDM1A is also associated with reduced expression of CDH1, which results in colon cancer metastasis." (PMID 29921310, 2018). "The promoter of CDH1, which encodes E-cadherin, also shows increased methylation in the inflamed mucosa of the ileum in patients with CD, which is associated with epithelial barrier dysfunction and a potentially increased risk of developing colon cancer." (PMID 41300823, 2025). "Our findings displayed that LSD1-target genes, namely, CABYR and CDH1 might be potential LSD1-target genes in colon cancer cells, and revealed the underlying mechanisms of invasion and metastasis in colon cancer." (PMID 28121627, 2017). "However, CDH1 T340A was reported to have a high association only with inherited and sporadic colon cancer in a Korean population." (PMID 27121310, 2016). "Mutations in CDH1 gene also may be associated with colon cancer." (PMID 32886433, 2020). "Knockdown of SERPINC1 in colon cancer cells inhibited TGFβ‐induced high expression of VIM, while knockdown of SERPINC1 in colon cancer cells restored TGFβ‐induced reduction of Cdh1 expression." (PMID 38923313, 2024). "The expression of the CDH1 gene in colon cancer cells increased with prolonged intervention with L. gasseri ATCC33323." (PMID 39250508, 2024). "In siNCKAP1-treated colon cancer cells, the intensity of CDH1 expression was significantly increased." (PMID 36639705, 2023). "When NCKAP1 expression was decreased by siRNA transfection in colon cancer cells, the levels of CDH1 and CTNNB1, which are known as epithelial marker among EMT markers, were increased." (PMID 36639705, 2023). "Low expression levels of CDH1 have also been reported in tumor-adjacent stroma of colon cancer patients." (PMID 36230846, 2022). "Recent research has indicated that ARID1A plays a significant function in colon cancer cell proliferation and migration via CDH1 regulation." (PMID 36420658, 2022). "In this study, we investigated the ARID1A‐VIM/CDH1 signalling axis's role in colon cancer proliferation and migration." (PMID 36420658, 2022). "In colon cancer, low E-Cadherin (CDH1/ECAD) and high N-Cadherin significantly correlated with local infiltration, tumor stage and vascular invasion." (PMID 32708431, 2020). "Our results on RAC1B regulation of CDH1 contrast with those of another study in human colon cancer cells in which E-cadherin expression was found to be negatively regulated by RAC1B." (PMID 31817229, 2019). "Survival curves based on ZEB1/CDH1 expression sustained the important role of the two genes in colon cancer prognosis, where combination between increased ZEB1 expression and decreased CDH1 levels significantly reduced the time of survival." (PMID 29352232, 2018). "In these terms, inhibition of ZEB1 and subsequent upregulation of CDH1 becomes an advantageous strategy especially in the case of patients with advanced stages of colon cancer." (PMID 29352232, 2018). "The results show that combination between high levels of miR-205 and increased expression of CDH1 is the best scenario in terms of survival rates for colon cancer patients representing the intention of the present therapeutic strategy." (PMID 29352232, 2018).
colon carcinoma (continued). "Study has also shown that Jarid2 is required TGF-β-induced epithelial-mesenchymal transition (EMT) through repression of CDH1 and miR-200 family genes in lung and colon cancers." (PMID 28445934, 2017). "This is also supported by the recent observation that KDM6A is necessary for H3K27me3 demethylation at the CDH1 locus in colon cancer cells." (PMID 29029452, 2017). "In conjunction with our previous work, we have demonstrated that ML327 is a novel small molecule that both represses MYC transcription and transcriptionally activates CDH1 in both colon cancer cells and neuroblastomas." (PMID 29207623, 2017). "We confirmed that relative to those with LGR5+ and KRASmut status, LGR5−/KRASwt colon carcinomas had decreased CDH1 and increased VIM and SLUG expressions, which are the expected changes in EMT biomarkers." (PMID 26744320, 2016). "In summary, we demonstrated that UA inhibited cell proliferation and migration and induced apoptosis in colon cancer cells by simultaneously modulating the MMP9/CDH1, Akt/ERK, COX-2/PGE2, p300/NF-κB/CREB2, and cytochrome c/caspase-dependent signaling pathways." (PMID 23737956, 2013). "Western blotting showed that TGF‐β could promote the expression of VIM and inhibit the expression of Cdh1 in colon cancer cells." (PMID 38923313, 2024). "Overall, these bioinformatic data strongly support our result that a change in E-cadherin (CDH1) expression may be an important mechanism in cancer recurrence and/or the death of colon cancer patients as a result of 5-FU resistance." (PMID 29731993, 2018). "Since the tested vitamin D analogues upregulate CDH1, they could be used to promote mesenchymal-to-epithelial transition and differentiation of residual colon cancer after conventional chemotherapy." (PMID 27314328, 2016). "Colon cancer cells transfected these miRs underwent a phenotype change from spindle-shaped to round-shaped in colon cancer cells, consistent with an increase in CDH1 protein levels." (PMID 25970424, 2015). "Notably, there was no increased risk of colon cancer in CDH1 carriers compared to that of the SEER population." (PMID 34949788, 2022). "According to data from cultured cells and animal models, we found a significant direct correlation between VDR and CDH1/E-cadherin RNA levels in human colon tumors, suggesting that VDR/1,25(OH)2D3 may contribute to the restoration of normal E-cadherin levels in human colon cancer." (PMID 24202444, 2013). "VIM and CDH1 appear to be ARID1A's molecular targets in colon cancer, which improve colon cancer cell viability, invasion and proliferation, especially in cells with ARID1A downregulation." (PMID 36420658, 2022). "In conclusion, CRC cells with ARID1A silencing had higher levels of VIM and lower levels of CDH1 expression, which are both positively correlated with ARID1A in colon cancer tissues." (PMID 36420658, 2022). "Prior studies found that HMGA1 regulates mesenchymal genes in colon cancer cells, such as Vimentin (VIM), N-cadherin (CDH2), E-cadherin (CDH1), and Fibronectin (FN1)." (PMID 34572547, 2021). "This is also shown for colon cancer cells where knockdown of CDH3 also resulted in reduced β-catenin expression and upregulated CDH1, called the cadherin switch." (PMID 31105876, 2019). "Kaplan–Meier analysis of survival between colon cancer patients with increased ZEB1 and decreased CDH1 expression vs. patients with low ZEB1 and high CDH1 values promotes the possible prognosis value for the combination between the two genes." (PMID 29352232, 2018). "In summary, the present study demonstrated the important role of miR-205 alone in suppression of EMT and restoration of the epithelial phenotype of in vitro colon cancer cells through ZEB1 targeting and CDH1 upregulation." (PMID 29352232, 2018). "This is notable since CDH1 and vimentin are involved in the EMT and cell motility control in human colon carcinoma." (PMID 28535802, 2017).